ASCL1 (achaete-scute family bHLH transcription factor 1)
Diseases named in the same sentence as ASCL1 in open-access papers (continued):
Sharing a sentence is not in itself a finding about the gene and the disease.
brain tumors (8 papers, 2018 to 2025). "Conversely, NB-FOXR2 lacked expression of the characteristic TFs and marker genes of EC-NB, except for ASCL1, known for its essential role in multiple CNS neural lineages and expressed across brain tumor types, and, to a lower level, HAND2." (PMID 39495206, 2025). "Taken together, this proof-of-principle study demonstrates a potential strategy for impeding brain tumor development by ASCL1-induced direct neuronal reprogramming." (PMID 31212628, 2019). "Our scRNA-seq of tens of thousands of FAC-sorted control and Ascl1-OE tumor cells from the GBM mouse model provides an unprecedented view of the highly dynamic transcriptomic landscape of brain tumors relevant to our understanding of the biology, plasticity, and malignancy of human GBMs." (PMID 39609428, 2024). "In summary, our comprehensive in vivo analyses of ASCL1 and OLIG2 loss- and gain-of-functions in primary brain tumors provide proof of concept of the combinatorial function of these two bHLH transcription factors in determining the lineage hierarchy, heterogeneity, and plasticity of GBMs." (PMID 39609428, 2024). "Here, we hypothesized that the loss of both ASCL1 and OLIG2 should prevent or significantly reduce brain tumor formation and/or progression, resulting in an increase in survival." (PMID 39609428, 2024). "With respect to brain tumors, ASCL1 is expressed in GBM, astrocytoma, and oligodendrogliomas." (PMID 34012965, 2021). "Notably, all GBM subtypes (proneural, classical, mesenchymal) were represented in all the mouse brain tumors, and as expected, the proneural subtype was expanded at the expense of the classical subtype with overexpression of ASCL1 due to its function as a proneural factor." (PMID 39609428, 2024). "More importantly, we also validated in the various mouse brain tumor types that genes of this transcriptional network and the cell types (NSC/NPC, astrocyte, OPC) associated with their function were altered accordingly in the absence or elevated levels of ASCL1 and/or OLIG2." (PMID 39609428, 2024). "Here, we show that induction of somatic mutations in subventricular zone (SVZ) progenitor cells leads to the dysregulation of ASCL1 and OLIG2, which then function redundantly and are required for brain tumor formation in a mouse model of GBM." (PMID 39609428, 2024). "Some of the most well-studied of these TFs in development and brain tumors are OLIG2, atonal bHLH transcription factor 1 (ATOH1) and Achaete-Scute family bHLH transcription factor 1 (ASCL1)." (PMID 34012965, 2021). "Previously, we and others have reported that the combined transcription factors (BRN2/ASCL1/ MYT1L or NGN2/SOX11) could reprogram human malignant glioma cells into terminally differentiated neuron-like cells and successfully impede brain tumor development." (PMID 31212628, 2019).
Parkinson disease (8 papers, 2013 to 2025). A progressive degenerative disorder of the central nervous system characterized by loss of dopamine producing neurons in the substantia nigra and the presence of Lewy bodies in the substantia nigra and locus coeruleus. "Certain transcription factors, e.g., Ascl1 and Lmx1b, seem to be required for specification of many brainstem regions that are susceptible to degeneration in early Parkinson’s disease." (PMID 28685157, 2017). "In Parkinson’s disease, Ascl1 is known to affect the developmental control of the coeruleus, a region thought to have neuroprotective effects through interaction with Phox2b." (PMID 36430421, 2022). "In cell cultures, Ascl1, Nurr1, and Lmx1a can induce dopaminergic neurons from fibroblasts derived from Parkinson’s disease patients." (PMID 31231645, 2019). "Another combination of NeuroD1, Ascl1, Lmx1a, and miR218 can produce dopaminergic neurons from astrocytes in an in vivo Parkinson’s disease mouse model." (PMID 31231645, 2019). "Regarding applying astrocyte transdifferentiation in Parkinson’s disease, one group used NeuroD1, Ascl1, Lmx1a, and miR-218 to convert astrocytes into dopaminergic neurons in the striatum of PD model mice, and the motor behavior symptoms of the mice were improved." (PMID 36138912, 2022). "Ascl1 has also been combined with Lmx1a and Nurr1 (ALN) to convert endogenous NG2 glia to inhibitory iNs in a dopamine-depleted (6-OHDA treated) mouse model of Parkinson’s disease." (PMID 34291049, 2021). "In contrast, the combination of a slightly different combination of TFs (Ascl1, NeuroD1, Lmx1a) and miR-218 efficiently programmed striatal astrocytes into functional induced dopaminergic neurons (iDANs), also in a 6-OHDA model of Parkinson’s disease." (PMID 34291049, 2021). "For example, in a mouse model of Parkinson’s disease, delivery of an adenovirus construct by CRISPR-SAM via injection into the brain resulted in successful reprogramming of astrocytes into functional neurons through the activation of differentiation factors Ascl1, Lmx1a, and Nr4a2." (PMID 40650152, 2025).
lung neuroendocrine tumors (7 papers, 2010 to 2025). "Finally, another SGK1 target, the epithelial sodium channel (ENaC), and specifically its alpha subunit, is a direct transcriptional target of the oncogene achaete-scute homolog 1 (ASCL1) in lung neuroendocrine tumors." (PMID 33266470, 2020). "Emerging molecular markers, such as protein expression of CD44, ASCL1, and OTP and TERT gene expression have shown prognostic value in lung NETs, alongside traditional markers like Ki-67 and somatostatin receptors." (PMID 40026252, 2025). "Recent studies have shown that pulmonary neuroendocrine tumor (NET) subgroups, defined by the transcription factors OTP and ASCL1, correlate with age, sex, and tumor location." (PMID 41196447, 2025). "While recent studies employing SCLC cell lines and mouse models indicated discordant expression patterns for ASCL1 and NEUROD131, our sequencing data of human high-grade neuroendocrine lung tumors revealed expression of both neuroendocrine lineage factors in class E." (PMID 29535388, 2018). "INSM1 has been reported to have excellent sensitivity and specificity for the diagnosis of lung NETs, and no cases of NSCLC have reported to be positive for ASCL1 immunostaining so far." (PMID 33968782, 2021).
astrocytoma (6 papers, 2019 to 2024). "In particular, our attention focused on Achaete-scute complex homolog 1 (ASCL1 or MASH-1), a basic helix-loop-helix transcription factor essential for neuronal differentiation, which has been associated with astrocytoma progression." (PMID 34257579, 2021). "On the contrary, ASCL1 and SOX4 expression were clearly more expressed in OLIG1+ cells in both the explored oligodendroglioma and astrocytoma samples." (PMID 33925547, 2021). "Lineage tracing experiments in mice have shown that ASCL1+ neural progenitors can be cells of origin of GBM and upregulation of ASCL1 and inhibition of NOTCH signaling characterize astrocytoma progression." (PMID 33076453, 2020). "High expression level of ASCL1 was observed in human astrocytomas, compared with human normal astrocytes." (PMID 31212628, 2019).
cervical cancer (6 papers, 2018 to 2025). A primary or metastatic malignant neoplasm involving the cervix. "Urine samples (27 controls, 30 CIN3 and 17 cervical cancer) were processed into 3 fractions and tested for 5 methylation markers (ASCL1, GHSR, LHX8, SST, ZIC1)." (PMID 32171935, 2020). "Methylation levels of several host cell genes, including ASCL1, LHX8, and ST6GALNAC5, increase with the severity of the underlying cervical disease and are particularly high in cervical scrapes of women with cervical cancer." (PMID 30360578, 2018). "Particularly for DNA methylation markers ASCL1 and LHX8, they were shown to yield a high sensitivity for cervical cancer detection, constituting a possible direct triage method for cancerous lesions in HPV-positive women." (PMID 40137778, 2025). "At a threshold corresponding to 75% specificity, CIN3+ sensitivity was 72.1% for ASCL1 and 73.8% for LHX8 and all samples from women with cervical cancer scored positive for these two markers." (PMID 30101434, 2018). "This study reports on primary DNA methylation analysis of host cell genes ASCL1, LHX8 or ST6GALNAC5 for the detection of cervical cancer and CIN3 in cervical scrapes from WLHIV." (PMID 30101434, 2018). "To further evaluate the performance of ASCL1, LHX8 and ST6GALNAC5 to detect CIN3 and cervical cancer, we calculated the positivity rates in the referral population for each histology subgroup at the fixed thresholds of 75% and 80% specificity." (PMID 30101434, 2018). "This indicates that single methylation marker analysis of ASCL1 or LHX8 would be an interesting primary cervical screening tool in WLHIV in low‐resource settings, as it detects the majority of CIN3 lesions that need treatment and provides a high reassurance against cervical cancer." (PMID 30101434, 2018).
embryonal carcinoma (4 papers, 2008 to 2019). A non-seminomatous malignant germ cell tumor characterized by the presence of large germ cells with abundant cytoplasm resembling epithelial cells, geographic necrosis, high mitotic activity, and pseudoglandular and pseudopapillary structures formation. "In this study, we explored regulation of ubiquitylation and degradation of Ascl1 in both neural stem cells and in P19 embryonal carcinoma cells that have long served as a model for studying proneural protein-mediated neuronal differentiation." (PMID 29545540, 2018). "For this, we used two models, looking at endogenous Ascl1 protein in NSCs and looking at overexpressed Ascl1 in mouse P19 embryonic carcinoma cells." (PMID 29545540, 2018).
medullary thyroid cancer (4 papers, 2018 to 2022). "Resveratrol increased Notch-2 mRNA, induced apoptosis and suppressed neuroendocrine marker ASCL-1 in medullary thyroid cancer (MTC)." (PMID 35408894, 2022). "Furthermore, treatment of medullary thyroid cancer cells MTC with Xn dose-dependently inhibited proliferation and down-regulated ASCL1, a possible malignant phenotype in thyroid cancer." (PMID 29872398, 2018).
non-small cell lung carcinoma (4 papers, 2019 to 2024). A group of at least three distinct histological types of lung cancer, including non-small cell squamous cell carcinoma, adenocarcinoma, and large cell carcinoma. "Almost 40% of LCNECs have molecular alterations often identified in non-small cell lung cancer (STK11, and KEAP1 mutations) with high expression of ASCL1 and neuroendocrine markers (defined as type I LCNEC)." (PMID 36553576, 2022). "Indeed, downstream targets of ASCL1 signalling have been suggested as viable drug targets to restrict NE non-small cell lung cancer growth." (PMID 31836808, 2019).
schizophrenia (4 papers, 2010 to 2023). A major psychotic disorder characterized by abnormalities in the perception or expression of reality. "We identified that prolonged stem cell quiescence in high inflammation schizophrenia may diminish the capacity to produce neuronal progenitor cells for brain repair, which is supported by the reduction in neuronal progenitor (ASCL1, DLX6-AS1) and immature neuron marker expression (DCX)." (PMID 34911938, 2021). "Investigating the inflammatory state of the SEZ has provided further insight into reduced quiescent neural stem cell (GFAPD) and neuronal progenitor cell marker expression (ASCL1, DLX6-AS1) in psychiatric disorders, particularly in schizophrenia." (PMID 34911938, 2021). "Specific to high inflammation schizophrenia, quiescent stem cell marker mRNA (GFAPD) was reduced, whereas neuronal progenitor (ASCL1) and immature neuron marker mRNAs (DCX) were decreased compared to low inflammation control and schizophrenia subgroups." (PMID 34911938, 2021).
anal carcinoma (3 papers, 2021 to 2025). "A cross‐sectional series of 176 tissue samples of anal cancer, AIN3, AIN2, AIN1 and control biopsies obtained in HIV‐negative women and men was tested for six methylation markers (ASCL1, LHX8, SST, WDR17, ZIC1 and ZNF582)." (PMID 33580586, 2021). "We recently validated that particularly the marker combinations ASCL1 and ZNF582, either or not combined with SST, had a very good performance for AIN3 and anal cancer detection in MSM living with HIV and a similarly good performance to detect AIN3 and cancer in HIV‐negative MSM." (PMID 40400293, 2025).
cervical disease (3 papers, 2018 to 2023). "The methylation levels of ASCL1 and LHX8 in HPV-positive self-collected samples increased with the severity of underlying cervical disease (Kruskal–Wallis omnibus test, both P values <0.0001)." (PMID 37100874, 2023). "Differences across cervical disease categories in methylation levels of ASCL1, LHX8 and ST6GALNAC5 were evaluated in the two South African study cohorts combined." (PMID 30101434, 2018). "Secondly, we investigated DNA hypermethylation of host cell genes ASCL1, LHX8, and ST6GALNAC5, as markers of advanced cervical disease, in relation to type-specific HPV infection." (PMID 30360578, 2018). "Hypermethylation levels of ASCL1,LHX8 and ST6GALNAC5 increased with severity of cervical disease." (PMID 30101434, 2018).
endometrial cancer (3 papers, 2017 to 2020). Primary or metastatic malignant neoplasm involving the endometrium (mucous membrane that lines the endometrial cavity). "It is appealing to suggest that ASCL1 and FGF12 methylation might have diagnostic potential (ability to discriminate between tumor and normal tissues) in both colorectal and endometrial cancer or reflect similarities in the biology underlying these cancer types." (PMID 28278225, 2017).
ischemia (3 papers, 2018 to 2023). A hypoperfusion of the BLOOD through an organ or tissue caused by a PATHOLOGIC CONSTRICTION or obstruction of its BLOOD VESSELS, or an absence of BLOOD CIRCULATION. "Finally, RBPJ deletion in striatal astrocytes from healthy mice induces a phenotype similar to a post-ischemia phenotype, namely an increase in ASCL1 and neuroblast generation." (PMID 37936690, 2023). "Similarly, after focal ischemia in vivo, endothelial cells upregulate ASCL1 prior to local astrocytic conversion to NSCs, and overexpression of ASCL1 in endothelial cells correlates with improved motor function." (PMID 39086680, 2023). "The authors also demonstrated that, as early as day 2 post-ischemia, astrocytes in the striatum express achaete-scute family BHLH transcription factor 1 (ASCL1), a proneural transcription factor." (PMID 37936690, 2023). "In our study, the trend of Ascl1 expression change was similar to Sp8, no statistically different at day 2 but higher than the contralateral side at day 7, 14, 28 and 60 post-ischemia." (PMID 30524246, 2018).
metastatic disease (3 papers, 2008 to 2025). "Similarly, CHRNA5 and ASCL1 were differentially expressed in SCLC with the metastatic disease." (PMID 30364292, 2018).
oligodendroglioma (3 papers, 2008 to 2024). A well-differentiated (WHO grade II), diffusely infiltrating neuroglial tumor, typically located in the cerebral hemispheres. "Another non-exclusive explanation for the expression of "neuronal" genes in oligodendrogliomas could rely on the fact that some genes involved in neurogenesis and classified as "neuronal" may also play a role in oligodendroglial development, e.g. ASCL1/MASH1." (PMID 18492260, 2008).
Cerebral ischemia (2 papers, 2022). Restriction of arterial blood supply to the brain associated with insufficient oxygenation to support the metabolic requirements of the tissue. "Brain endothelial cells showed highest mRNA level of Ascl1 after cerebral ischemia when compared to other cell types." (PMID 36535938, 2022).
colorectal cancer (2 papers, 2018 to 2023). A primary or metastatic malignant neoplasm that affects the colon or rectum. "Despite this, enrichment for disease-associated DEGs in the ASCL1-del mutant line showed that they are associated with colorectal cancer." (PMID 37958729, 2023).
demyelinating disease (2 papers, 2021 to 2022). A broad group of disorders that affect the myelin sheaths that cover the neurons. "If so, Ascl1-induced expansion of the OPC pool could be a strategy for regenerating oligodendrocytes in demyelinating diseases." (PMID 36532282, 2022). "Firstly, oligodendrocytes have been demonstrated to emerge from the gliogenic pathway, driven by over-expression of the Achaete-Scute Family Homolog 1 (Ascl1; Mash1) transcription factor, a mechanism that may prove to be important in demyelinating diseases." (PMID 34679362, 2021).
gastritis (2 papers, 2022 to 2023). Inflammation of the stomach. "Following Helicobacter pylori infection in mice inducing gastritis, transcription factor Achaete-Scute Family BHLH Transcription Factor 1 (ASCL1) increased AQP5 expression, which was responsible for the activation of the WNT/β-catenin signaling pathway." (PMID 36768212, 2023). "In this context, our study was performed to delineate the involvement of AQP5 and ASCL1 in H. pylori infection during gastritis." (PMID 35538066, 2022). "These evidences support that H. pylori infection triggered the inflammatory response and apoptosis of GECs to induce the occurrence of gastritis by activating Wnt/β-catenin pathway via upregulation of ASCL1 and AQP5." (PMID 35538066, 2022). "Data obtained in our study elaborated that H. pylori infection facilitated inflammatory response and apoptosis of GECs to promote gastritis through the activation of AQP5/ASCL1/WNT/β-catenin axis." (PMID 35538066, 2022). "As per differential analysis results of GSE106656, ASCL1 was highly expressed in IM patients in contrast to gastritis patients, and was positively correlated with AQP5 expression." (PMID 35538066, 2022). "Taken together, the key findings of the present study demonstrate that H. pylori infection activated WNT/β-catenin signaling pathway by upregulating ASCL1/AQP5 to induce gastritis." (PMID 35538066, 2022). "Our finding unveiled that ASCL1 was highly expressed in gastritis and H. pylori infected-GECs." (PMID 35538066, 2022). "Moreover, further mechanistic investigation data in this study unraveled that H. pylori induced AQP5 expression by upregulating ASCL1 that was highly expressed in gastritis." (PMID 35538066, 2022). "However, the translation of the finding into clinical scenario may be limited by the lack of verification of the expression and distribution of AQP5 and ASCL1 in clinical samples of gastritis and IM, which should be further studied in future investigations." (PMID 35538066, 2022). "Gastritis mouse models were established by H. pylori infection, followed by determination of AQP5 and ASCL1 in gastric mucosa." (PMID 35538066, 2022). "Therefore, the purpose of this study is to evaluate the mechanistic significance of ASCL1 and AQP5 in H. pylori infection of gastritis." (PMID 35538066, 2022). "However, there existed no reports about the role of ASCL1 in H. pylori infection and gastritis." (PMID 35538066, 2022).